TTF1 (transcription termination factor 1)
Diseases named in the same sentence as TTF1 in open-access papers (continued):
Sharing a sentence is not in itself a finding about the gene and the disease.
tumor (continued). "TTF‐1 might have an effect on the production of mucus, that is, TTF‐1‐negative/weakly positive tall column‐like tumour cells were able to produce much more mucus." (PMID 38616354, 2024). "Tall column‐shaped tumour cells were negative or weakly positive for thyroid transcription factor‐1 (TTF‐1) and strongly positive for ALK mutation, whereas quasi‐circular tumour cells were positive for TTF‐1 and less positive for ALK mutation." (PMID 38616354, 2024). "Tumours lacking any adenocarcinoma architectural differentiation, namely purely solid pattern tumours, are typically classified as adenocarcinoma on the basis of immunohistochemical expression of TTF-1 alone." (PMID 37045996, 2023). "Xenografts of A549‐SUCLG2 cells displayed a reduced tumor weight and volume compared with those of A549‐SUCLG2WT, and the IHC results demonstrated that the expression of Ki67 was decreased and that of TTF1 was increased in SUCLG2K93R mutant tumors compared with SUCLG2WT tumors." (PMID 37904651, 2023). "In accordance with the WHO Classification of Tumors of the Lung, Pleura, Thymus, and Heart, at our hospital, if adenocarcinoma or squamous is diagnosed at the time of hematoxylin and eosin (HE) staining of tumor tissue, no further immunostaining, including TTF-1, is performed." (PMID 36614938, 2022). "Some tumor sections were immunostained with ready-to-use primary antibodies against broad-spectrum cytokeratin (CK), vimentin, CD117, CK5/6, CK7, P40, P63, thyroid transcription factor-1 (TTF-1), smooth muscle actin, CD56, napsin A, synaptophysin, S-100, and Ki-67 (Maixin, Fuzhou, China)." (PMID 35550474, 2022). "In addition, TTF-1 staining is no longer performed in all cases, because more tumor tissues are now used for driver gene testing and PD-L1 immunostaining." (PMID 36614938, 2022). "TTF-1 tends to be positive in peripheral tumours but negative in central tumours." (PMID 36233825, 2022). "Further, 130 cases in which TTF-1 immunostaining of tumor tissue was not performed were excluded." (PMID 36614938, 2022). "Acinar ADC LF20 maintained the CK7+/CK20−/TTF-1+ staining pattern throughout all passages, while acinar ADC sample LF19 preserved the original expression of the primary tumor until passage X1 but lost CK7 and TTF-1 expression in passage X2, and sample LF01 lost CK7 expression." (PMID 34198671, 2021). "Additionally, TTF-1 exhibited strong nuclear immunoreactivity for glandular tumor cells but was negative for squamous cells." (PMID 34941144, 2021). "Furthermore, the tumor cells were positive for cytokeratin (CK) 19; partially positive for thyroid transcription factor-1 (TTF-1); and negative for Pax-8, Napsin A, CDX-2, SATB2, and terminal deoxynucleotidyl transferase (TdT)." (PMID 33847622, 2021). "In addition, the tumor cells were multifocally moderately positive for CD56, scattered moderately positive for S-100, and negative for CD20, PAX8, actin (SM), chromogranin A, synaptophysin, TTF-1, vimentin, and thyroglobulin." (PMID 32756201, 2020). "Immunohistochemical (IHC) staining was performed using thyroid transcription factor-1 (TTF-1), paired box protein 8 (PAX8), cytokeratin 20 (CK20), caudal-related homeobox transcription factor-2 (CDX-2) and villi protein (Villin) in order to clarify the origin of the tumor." (PMID 32375670, 2020). "By immunohistochemistry, the tumor cells are often negative but can be focally positive for thyroglobulin; however, they are positive for TTF1, PAX8 (variable staining intensity), and estrogen and progesterone receptors and are negative for CK20 and calcitonin." (PMID 32632840, 2020).
tumor (continued). "These cells were negative for two lung adenocarcinoma (LUAD) markers; TTF1 and Napsin A, and IHC analysis could not determine the primary organ of the tumor." (PMID 30634950, 2019). "Immunohistochemically, tumor cells were negative for thyroid transcription factor-1 (TTF-1)." (PMID 30999697, 2019). "Interestingly, the tumor contained a 3 mm focus of a lesion staining positive for Thyroid Transcription Factor-1 (TTF1), Thyroglobulin, and was negative for RCC marker." (PMID 28249616, 2017). "In contrast, no detectable levels of GLUT1 were found in TTF-1-positive ADC tumours." (PMID 28548087, 2017). "The results from Q-PCR and western blot indicated that the mRNA expression of E-cadherin and TTF-1 was downregulated, while the expression of fibronectin and α-SMA was increased in CCA tissues, which indicated that during the progression of CCA, the tumor cell exhibited activated MET phenotype." (PMID 29084594, 2017). "However, the tumor cells were completely negative for other common neuroendocrine markers such as chromogranin A, synaptophysin, and TTF-1." (PMID 28103943, 2017). "Thus, reduced expression of sortilin in NSCLC patients was correlated with increased cellular proliferation, accelerated tumor growth, and TTF-1–negative poorly differentiated tumors." (PMID 29084952, 2017). "The tumor cells were positive for TTF-1, PAX8, Napsin-A and were negative for thyroglobulin." (PMID 27774331, 2016). "The tumor cells were negative for thyroglobulin and showed only focal staining for TTF-1, which often occurs in anaplastic transformation, as studies have demonstrated loss of thyroglobulin and TTF-1 expression in ATC." (PMID 26351607, 2015). "The tumor cells were negative for TTF-1, thyroglobulin, CD10, WT-1, SMMHC, CEA, and S-100." (PMID 25133003, 2014). "Additionally, we identified the tumor cluster cells were surrounded by the connective tissue which was negative for TTF-1 or CK." (PMID 21955603, 2011). "Immunohistochemistry has a central role for the diagnosis of SCCB through the staining of tumour components by antibody markers targeting the following antigens: neuron-specific enolase (NSE), chromogranin, synaptophysin, serotonin, cytokeratin, S-100 protein, TTF1, EGFR and C-KIT." (PMID 22078012, 2011). "In adenocarcinoma portion, the tumor cells formed irregular-shaped glands with cytologically malignant cells infiltrating in fibroblastic stroma, and no TTF-1-positive round cells could be observed in this portion." (PMID 21599956, 2011). "Since the immunohistochemical analysis was negative for the thyroid transcription factor-1 protein (TTF-1) and was positive for cytokeratin 20, a primary adenocarcinoma of the lung was unlikely and the tumour was finally attributed to the minor salivary glands as site of origin." (PMID 18667060, 2008). "While the majority of tumor cells stained positive for PD-L1, no TTF1 protein could be detected." (PMID 37228492, 2023). "One tumor with acinar predominant histology and a missense SMARCA4 variant (patient Cd) and one with solid predominant histology and a combination of truncating and missense SMARCA4 variants (patient Ci) were TTF-1 negative, while the remaining tumors were TTF-1 positive." (PMID 35964518, 2022). "In the cases investigated, several neoplasms, previously diagnosed as ccRCC, showed a thyroid-like aspect, characterised by an eosinophilic content cystic-follicular architecture, with negativity for TTF-1 and thyroglobulin and without, as already mentioned, a specific immunohistochemical pattern." (PMID 36611378, 2022). "In addition, patients whose tumour exhibited no expression of NKX2‐1/TTF‐1 exon 1 had significantly shorter median OS (log‐rank test, p = 0.0306; Breslow–Wilcoxon test, p = 0.0032); however, these differences were barely significant compared to TTF‐1 protein expression." (PMID 34014042, 2021).
tumor (continued). "Both tumor components stained negative for p40, p63, CK5/6, and chromogranin A. Notably, small cell neuroendocrine carcinoma of the cervix can stain for TTF-1." (PMID 41589095, 2026). "Cytopathological analysis of the lymph nodes showed tumor cells positive for p16, CAM5.2, TTF-1, synaptophysin, and CD56, and negative for CD45, p40, chromogranin, Napsin A, p63, and CK5/6." (PMID 41589095, 2026). "Immunohistochemically, the tumor cells were positive for GFAP and S‐100 protein, weakly positive for SOX2, focally positive for synaptophysin, and negative for TTF‐1, neurofilament protein, NeuN, EMA, chromogranin, and BCOR." (PMID 39492623, 2025). "Tumor cells tested negative for SMARCA4 but were positive for Chromogranin-A(CgA), Synaptophysin (SYN), Insm-1, TTF-1 (partial), and Ki67 (90%)." (PMID 40661782, 2025). "On immunostaining, tumor cells were positive for GATA3, CD10, calretinin, TTF-1, and Pax-8 at various degrees, but were negative for ER." (PMID 39896229, 2025). "Immunohistochemically, the tumor cells were positive for CK5/6, P40, and Ki-67 (approximately 45% in hot spots) and negative for TTF-1 and napsin A." (PMID 40746613, 2025). "Immunohistochemically, tumor cells were positive for AE1/AE3 cytokeratin, EMA (cytoplasmic pattern), and TTF-1 (nuclear pattern), and were negative to neuroendocrine markers (CgA and Syn) and S100." (PMID 39851953, 2025). "Immunostains demonstrated tumor cells were positive for CK7 and CDX2, but negative for CK20, TTF‐1, and GATA‐3." (PMID 41473421, 2025). "In our case, the tumor exhibited positive staining for CK5/6, P40, P63, and CK7, while showing negative staining for Napsin A, TTF-1, CD56, Chromogranin A, Synaptophysin, Pax-8, thyroglobulin, and vimentin." (PMID 40061900, 2025). "On immunohistochemical (IHC) staining, tumor cells showed patchy expression of CD56, but the tumor was negative for broad-spectrum keratins, PAX8, TTF1, thyroglobulin, calcitonin, HBME-3, CEA, PTH, GATA3, p63, SOX10, and S-100." (PMID 40277780, 2025). "Immunohistochemically, the tumor was positive for vimentin, EMA, PgR, TTF-1, and somatostatin receptors-2, and negative for cytokeratin, Bcl-2, CD34, and S-100, with a Ki-67 index of approximately 5%." (PMID 40265140, 2025). "Immunohistochemistry revealed that the tumor cells were positive for CEA, CK7, and TTF‐1 and negative for CK20, confirming pulmonary colloid adenocarcinoma." (PMID 41473421, 2025). "The tumor's immunoprofile, positive for CK8/18, TTF-1, and Napsin A, and negative for gastrointestinal markers, was decisive in confirming the pulmonary origin of the adenocarcinoma." (PMID 41503294, 2025). "The tumor cells were positive for CKpan and CK7, while being negative for CgA, Syn, thyroid transcription factor-1 (TTF-1), P63, and P40." (PMID 38335397, 2024). "Primary tumor cells were diffusely positive for CK7, CK20, Cam5.2 and negative for SOX10, TTF1, PSA, and CDX2." (PMID 38831459, 2024). "TTF-1 positive cases were equally distributed in right and left lung (TTF-1 positive lung NET: 46 right-located and 32 left-located; TTF-1 negative tumours: 43 right-located and 34 left-located; p = 0.694)." (PMID 37775725, 2024). "On immunohistochemistry, the tumor cells were positive for S100P and SOX-10 and focally positive for HMB-45 and Melan A. Tumor cells were negative for CK, EMA, SMA, TTF1, PAX8, GATA3 and SALL4." (PMID 38509523, 2024). "Immunohistochemistry showed that the tumor cells were positive for CK7, P63, P40, CK5/6, and PCK; slightly positive for EMA; and negative for thyroid transcription factor-1 (TTF-1), napsin A, CD10, Vimentin, and smooth muscle actin." (PMID 37352028, 2023). "A triple-collision tumor with MCC, SCC in situ, and basal cell carcinoma with an unusual CK20 negative and TTF-1 positive immunophenotype has also been reported." (PMID 37058042, 2023).
tumor (continued). "Immunohistochemically, tumour cells were diffusely positive for CD10, EMA, and vimentin, and negative for CK7, TTF-1, renal cell antigen, and E-cadherin." (PMID 36900135, 2023). "Immunohistochemistry staining showed the tumour was positive for AE1/3, CK7, GATA-3 and GCDFP-15; and was negative for CK20, PAX-8, CDX-2, WT-1, TTF-1, mammaglobin and BRAF V600E." (PMID 36871042, 2023). "Immunophenotypically, the tumor was positive for Cytokeratins Oscar and 7, GATA3, GCDFP, HER2, and an androgen receptor but negative for CK20, S100, p40, Melan A, CDX2, TTF1, ER, SATB2, DOG1, synaptophysin, and chromogranin." (PMID 37886914, 2023). "In the presented case, there was no doubt about the malignant nature of the tumor; however, the positive expression of PTH and the absence of TTF-1, thyroglobulin, CK7, and HBME-1 expression made it possible to clarify its origin." (PMID 37183888, 2023). "In this study, for all cases tested, the tumor cells are positive for PAX8, GATA3, TTF1, and luminal CD10, and are negative for ER and PR, consistent with the immunohistochemical results previously reported." (PMID 35865471, 2022). "As per immunohistochemistry, the tumor cells were diffusely positive for SF-1 and Ki-67, partially positive for inhibin, and negative for CAM5.2, CK7, CK20, C-KIT, CD30, LCA, GATA-3, TTF-1, and PAX8." (PMID 36335378, 2022). "TTF-1 was positive in 263 (73.3%) patients and negative in 91 (25.3%), and TTF-1 was not performed in 5 patients because the tumor material was not sufficient in order to favor molecular biology testing." (PMID 35885495, 2022). "The tumor cells were negative for vimentin, CDX2, estrogen receptor (ER), CK20, chromogranin, TTF-1, smooth muscle actin (SMA), synaptophysin, S100, and calponin." (PMID 35168684, 2022). "Tumor cells were negative for vimentin, CK7, smooth muscle actin, napsin A, synaptophysin, S-100, and TTF-1." (PMID 35550474, 2022). "Immunohistochemistry showed that the tumor cells were positive for CK7, P63, P40, and CK5/6, and negative for TTF-1, PAX-8, S-100, SMA, Napsin A, HMB45, Syn, and CgA." (PMID 35346255, 2022). "Immunohistochemistry showed that the tumor cells were immunoreactive for GATA3, TTF1, and napsin A and nonimmunoreactive for p40." (PMID 33542845, 2021). "In this case, the tumor cells expressed CK7 and weakly expressed TTF‐1; however, the mucous cells were negative for both markers; all cells generally had a low Ki‐67 proliferating index." (PMID 33960670, 2021). "IHC analysis of biopsied tumor tissue revealed positive CK7 and negative TTF‐1 and napsin‐A immunoreactivity, confirming a diagnosis of SCC." (PMID 33565277, 2021). "Immunohistochemistry showed that the tumor cells were positive for calcitonin, chromogranin A, synaptophysin, CD56, and TTF-1, but negative for other lineage-specific markers." (PMID 34838061, 2021). "The cell block was tested by IHC and the identified tumor cells were found to be reactive for BEREP4, K7, and CDX2 and negative for TTF1 and calretinin." (PMID 34178989, 2021). "The IHC analysis of the CASTLE tumor shows a strong positive staining with CD5, p63, and cytokeratin but negative staining with thyroglobulin, TTF1, and calcitonin." (PMID 34399813, 2021). "Immunohistochemically, the tumor cells express CK7 and transcription termination factor 1 (TTF-1) but not thyroglobulin, which supports the diagnosis." (PMID 34871272, 2021). "The average tumor grade was also increased, with c-Junfl/fl; lsl-K-RasG12D animals exhibiting grade 4 LADCs, which were HMGA2+/TTF-1– and not observed in controls, and some additionally showing lepidic predominant adenocarcinoma (formerly BAC) lesions." (PMID 34236045, 2021). "In our case, we found that the tumor specimen was positive for CK, CK7, P63, and vimentin, but negative for EMA, TTF-1, smooth muscle actin, desmin, carletinin, and D2-40." (PMID 34766593, 2021).
tumor (continued). "The tumor cell immunophenotype was positive for vimentin, EMA and negative for CK-pan, TTF-1, CAM5.2, S-100, calponin, SMA, desmin, ALK, CD31 and CD34." (PMID 32039736, 2020). "The immunohistochemical examination indicated that the tumor had metastasized from the primary esophageal SCC, because its cells were positive for p63 and p40 and negative for SP-A and TTF-1." (PMID 32757102, 2020). "Immunohistochemically, the tumor cells are positive for GFAP, CK7, ER, and PR, but negative for S-100, TTF-1, CAM5.2, and CK20." (PMID 31689791, 2019). "Tumor cells were positive for vimentine and EMA, and were negative for SMA, TTF-1, Chromogranin A, synaptophysin." (PMID 30285886, 2018). "The tumor cells were negative for synaptophysin, SMA (smooth muscle actin), TTF-1 (thyroid transcription factor-1), Chromogranin A, desmin, GFAP, WT-1 (Wilm’s tumor gene-1), HBME-1 (Hector Battifora mesothelial epitope-1)." (PMID 30285886, 2018). "Tumor cells were positive for hepatocyte, glypican-3, and pan-CK, and focally positive for CK20 and CEA but were negative for CK7 and TTF-1, CA 19-9, p63, CDX2, and OCT3/4." (PMID 30268151, 2018). "The tumor cells were negative for CK20, synaptophysin, chromogranin A, transthyretin, TTF-1, RCC, thyroglobulin, and CD10." (PMID 30340515, 2018). "Guiping Qin demonstrated that the tumor cells are positive for vimentin, CK, CgA, syn, CEA, calcitonin, HMB-45, and S-100 and negative for TG and TTF-1." (PMID 30424779, 2018). "The tumor cells of MP-MTC were positive for melanin biomarkers, TTF-1 and exhibited no genetic features." (PMID 30424779, 2018). "Tumor cells were negative for CK7, CK5/6, thyroid transcription factor-1 (TTF-1), CD20, CD3, CD5, terminal deoxynucleotidyl transferase (TdT), and CD99." (PMID 28602157, 2017). "In all KL tumours we examined, p63 and CK5 were co-localized in SqCC tumours, whereas TTF-1-expressing tumours (ADC) were negative for SqCC marker CK5 expression and vice versa." (PMID 28548087, 2017). "In contrast, tumor cells in non-TRU-type adenocarcinoma had cuboidal or columnar cytoplasm with a flat apical border and were TTF-1-negative." (PMID 27575252, 2016). "In contrast, the cells in the intrapulmonary tumor were positive for TTF-1 and Ber-EP4, but negative for calretinin and D2-40, thus confirming that the latter tumor was PAC." (PMID 27091358, 2016). "The tumor cells were immunoreactive for cytokeratin 7 (CK7), thyroid transcription factor-1 (TTF-1), and napsin A and were negative for CD20, CDX2, P63, chromogranin, synaptophysin, and CD56." (PMID 26425638, 2015). "Immunohistochemical analysis showed positive cytoplasmic staining of the tumor cells for HMB-45, Tyrosinase, and MART1, although the expression of TTF-1 in tumor cells was negative." (PMID 26376781, 2015). "Tumor cells of scalp nodules were positive for CDX2, but negative for TTF-1 and CK20 in this case; therefore, scalp nodules were not MCC and originated from the colon." (PMID 24884973, 2014). "The tumor cells were negative for CK20 and EMA, as well as for HCC marker, RCC marker, TTF-1, ER, PR, CA-125, and chromogranin A." (PMID 24955270, 2014). "In our case, the tumor cells showed negative immunoreactivity for ER, PR, HER2/neu and GCDFP-15, and positive for TTF-1, CK-7 and Napsin A." (PMID 25274100, 2014). "In our case the tumor was positive for CEA, CK 7 and TTF-1 and negative for CK 20, ER, COX2, CK 14, CDX2, and MUC2." (PMID 24716057, 2014). "Immunohistochemical studies revealed that tumor cells were strongly immunoreactive for PTH and negative for calcitonin, TTF-1, and thyroglobulin, thus confirming that the tumor cells were parathyroid in origin." (PMID 23936709, 2013). "Immunohistochemistry of the tumor cells revealed positive staining for CEA and negative for thyroglobulin and thyroid transcription factor-1 (TTF-1)." (PMID 23760305, 2013). "In this report, tumor cells showed positive reaction for E-ca, CDX2 and MUC1, and negative reaction for MUC2, Hep Par1 and TTF-1." (PMID 23938020, 2013).